EPHA3 (EPH receptor A3)
Description:
Receptor tyrosine kinase which binds promiscuously membrane-bound ephrin family ligands residing on adjacent cells, leading to contact-dependent bidirectional signaling into neighboring cells. The signaling pathway downstream of the receptor is referred to as forward signaling while the signaling pathway downstream of the ephrin ligand is referred to as reverse signaling. Highly promiscuous for ephrin-A ligands it binds preferentially EFNA5 (By similarity). Upon activation by EFNA5 regulates cell-cell adhesion, cytoskeletal organization and cell migration. Also activated by EFNA1, inhibiting epithelial-to-mesenchymal transition of cardiac cells and playing a role in heart development. Involved in the retinotectal mapping of neurons. May also control the segregation but not the guidance of motor and sensory axons during neuromuscular circuit development (By similarity).
Synonyms: EK4; hEK4; ETK; ETK1; HEK; TYRO4
Tractability: Small molecule: an approved drug acts on it; a structure with a bound ligand is known; a high-quality ligand is known; it has a high-quality binding pocket; it belongs to a druggable protein family. Antibody: a drug acting on it is in phase 1 trials; UniProt places it where antibodies can reach, with high confidence; its Gene Ontology location is reachable by antibodies, with high confidence; UniProt predicts a signal peptide or a membrane-spanning region; the Human Protein Atlas places it where antibodies can reach. PROTAC: it is named in the literature on targeted protein degradation; ubiquitination databases record sites on it; its protein half-life has been measured; a small molecule that binds it is known.
Target class: Tyrosine protein kinase Eph family; Protein Kinase; TK protein kinase group; Kinase; Enzyme
Gene: Protein-coding gene on chromosome 3 (89,107,522 to 89,482,437, forward strand). Ensembl gene ENSG00000044524.
Subcellular location: Cell membrane (Isoform 1); Secreted (Isoform 2)
Subcellular location (Human Protein Atlas): Cytosol; Nuclear membrane; Plasma membrane; Actin filaments; Nucleoplasm
Pathways (Reactome):
Developmental Biology: EPH-Ephrin signaling; EPH-ephrin mediated repulsion of cells; EPHA-mediated growth cone collapse
Gene Ontology:
Molecular function: ephrin receptor activity; GPI-linked ephrin receptor activity; protein binding; transmembrane-ephrin receptor activity; ATP binding; protein kinase activity; protein tyrosine kinase activity; transmembrane receptor protein tyrosine kinase activity
Biological process: cellular response to retinoic acid; ephrin receptor signaling pathway; negative regulation of endocytosis; peptidyl-tyrosine phosphorylation; positive regulation of neuron projection development; positive regulation of protein localization to plasma membrane; regulation of actin cytoskeleton organization; regulation of cell-cell adhesion; regulation of focal adhesion assembly; regulation of microtubule cytoskeleton organization; axon guidance; cell migration; fasciculation of motor neuron axon; fasciculation of sensory neuron axon; negative regulation of epithelial to mesenchymal transition; regulation of epithelial to mesenchymal transition; cell surface receptor protein tyrosine kinase signaling pathway
Cellular component: early endosome; extracellular region; plasma membrane; dendrite; membrane
Genetic constraint (gnomAD): Loss-of-function variants: 40 observed, 102.52 expected, observed/expected ratio (o/e) 0.39, 90% interval 0.3 to 0.51. The upper end of that interval is the gene's LOEUF score, 0.51, which puts it in group 2 of 6, group 1 being the genes least tolerant of losing a copy. Missense variants: 1,135 observed, 1,215.7 expected, observed/expected ratio (o/e) 0.93, 90% interval 0.89 to 0.98. Synonymous variants: 444 observed, 429.59 expected, observed/expected ratio (o/e) 1.03, 90% interval 0.95 to 1.12.
Homologues: Orthologues: chimpanzee EPHA3 (99% identical), macaque EPHA3 (99% identical), pig EPHA3 (98% identical), rabbit EPHA3 (98% identical), mouse Epha3 (97% identical), rat Epha3 (93% identical), dog EPHA3 (93% identical), guinea pig EPHA3 (91% identical), tropical clawed frog epha3 (85% identical), zebrafish epha3l (80% identical). Paralogues in human: EPHA5 (67% identical), EPHA6 (63% identical), EPHA4 (63% identical), EPHA7 (63% identical), EPHA8 (57% identical), EPHB2 (56% identical), EPHB3 (56% identical), EPHB1 (55% identical), EPHA2 (50% identical), EPHB4 (48% identical), EPHA10 (47% identical), EPHA1 (42% identical), and 41 more.
Diseases named in the same sentence as EPHA3 in open-access papers:
EPHA3 is named in the same sentence as 107 diseases in open-access papers, as found by Europe PMC text mining. Sharing a sentence is not in itself a finding about the gene and the disease. The quoted sentences say what the papers report.
glioblastoma (43 papers, 2010 to 2025). The most malignant astrocytic tumor (WHO grade IV). "Mutations in EphA3 have been well characterized in multiple cancers including lung, colon, melanoma, and glioblastoma." (PMID 39111833, 2024). "Higher EphA2 and EphA8 expression were associated with poorer, while higher EphA3 expression was associated with better, prognosis in patients with glioblastoma, respectively." (PMID 37146061, 2023). "Several Eph receptors, including EphA5 and most commonly EphA3, are mutated in lung cancer, and EphA3 mutations have also been reported in melanoma, glioblastoma, colon, liver, pancreatic, and ovarian cancers." (PMID 36830852, 2023). "For instance, high expression of EphA2 and EphA3 has been linked to poor survival identified in glioblastoma multiforme (GBM)." (PMID 35215250, 2022). "Mutations of EphA3 were identified as candidate cancer risk genes in breast cancer, colon cancer, lung cancer, glioblastoma, melanoma, and pancreatic carcinoma." (PMID 34021125, 2021). "EphA3 is overexpressed in various tumor cells and is implicated in the maintenance of tumor-initiating cells in glioblastoma and leukemia." (PMID 34021125, 2021). "EPHA3 is recurrently mutated in adenocarcinoma and has been implicated in renal carcinoma, glioblastoma, colorectal, breast and lung cancer." (PMID 21494657, 2011). "For instance, mutations have been identified in EphA3 in melanoma and glioblastoma, and EphA3, EphA4, EphA7, and EphB6 in colorectal cancers." (PMID 20224755, 2010). "EPHA3 encodes a protein tyrosine kinase receptor and its expression has been associated with high invasive capacity and poor overall survival in hepatocellular carcinoma, gastric cancer, and glioblastoma." (PMID 29383146, 2017). "EphA3 was subsequently found to be widely expressed also in myeloid malignancies, and in tumors of mesenchymal origin, such as melanoma, sarcoma and glioblastoma, where it is particularly associated with a more mesenchymal phenotype, and progenitor or stem cell-like tumor cells." (PMID 32397088, 2020). "In gliomas, particularly glioblastoma multiforme, overexpression of EphA2 and EphA3 correlates with higher tumor grade and increased invasiveness." (PMID 41200151, 2025). "Several preclinical studies reported that anti-EphA3 CAR-T cells are effective against glioblastoma." (PMID 40688499, 2025). "A phase I clinical trial was conducted targeting glioblastoma patients with a drug (NCT03374943) that regulates the protein level of EPHA3, which we identified as the final player in the epigenetic regulome associated with the aggressiveness of HCC." (PMID 39617786, 2024). "A phase I clinical trial evaluating the anti-EPHA3 monoclonal antibody ifabotuzumab in patients with recurrent glioblastoma demonstrated its efficacy in targeting the tumor microenvironment while sparing normal tissues." (PMID 39617786, 2024). "The increased expression of ephrin receptor A2 (EphA2) and ephrin receptor A3 (EphA3) correlated with poor prognosis in patients with glioblastomas." (PMID 37146061, 2023). "On the contrary, in glioblastoma EphA3 is overexpressed and involved in maintaining tumor cells in a less differentiated state." (PMID 37434266, 2023). "Our previous studies have designed and developed TMZ short-chain ester derivative TMZ4e (TBE) loaded NPs functionalized with anti-EphA3 for glioblastoma targeting, which showed excellent GBM targeting effect and anti-glioma activity." (PMID 36059989, 2022). "The bispecific antibody against EphA3 lessens the tumorigenesis of recurrent glioblastoma by downregulating ERK signaling pathway." (PMID 36578556, 2022). "For this purpose, we used a transmembrane receptor gene, EPHA3, as a model, and the QCell human glioblastoma cell line HW1 as the source of the gene." (PMID 35324780, 2022). "For example, the EphA3 tyrosine kinase receptor is highly expressed on glioblastoma cells with stem-like properties, but is present in low levels in healthy adult tissue." (PMID 32542524, 2021).
glioblastoma (continued). "A clinical trial (NCT03374943) of monoclonal antibodies against EphA3 in glioblastoma patients has started." (PMID 32542524, 2021). "We have also recently observed an analogous expression pattern for two other glioblastoma antigens, EphA3 and α‐dystroglycan, in gliosarcoma." (PMID 33082953, 2020). "A bispecific anti-EphA2/EphA3 antibody triggers internalization of EphA2 and EphA3 leading to reduced tumorigenicity of glioblastoma." (PMID 32629797, 2020). "Although there have been few studies on EphA3 and PCa prognosis, in mesenchymal glioblastoma, hepatocellular carcinoma, gastric carcinoma, and multiple myeloma, it has been confirmed that high EphA3 expression is associated with a poor prognosis." (PMID 30958616, 2019). "Ephrin type-A receptor 3 (EPHA3) tyrosine kinase antibody-modified polylactide-co-glycolide (PLGA) nanoparticles (NPs) were developed to target glioblastoma via nose-to-brain delivery." (PMID 30176744, 2018). "Combined expression of EphA2, EphA3, EphB2, and IL-13RA2 is observed in almost 100% of patients with glioblastoma patients." (PMID 30366424, 2018). "In glioblastoma multiforme, EPHA3 has exhibited highly expression in undifferentiated mesenchymal cells and has been especially assigned a kinase-independent oncogenic role based on its modulating mitogen-activated protein kinase (MAPK) signaling." (PMID 27101199, 2016). "Studies have shown that EPHA3 exhibits abnormal expression in a variety of tumors, such as colorectal carcinoma, glioblastoma multiforme, melanoma, and hepatocellular carcinoma." (PMID 27101199, 2016). "Additionally, EphA3-targeted chimeric antigen receptor (CAR)-T cells demonstrated robust antigen-specific killing of human glioblastoma and diffuse midline glioma cell lines in animal models." (PMID 40688499, 2025). "The previous study, exploring the mechanism underlying Eph receptor induce cancer recurrence demonstrated that co-expression of EphA2 and EphA3 led to the high clonogenicity and tumorigenic potential in recurrence of glioblastoma which has been shown in both in vitro and in vivo models." (PMID 32093644, 2020). "Intriguingly, these two molecules also show a perivascular distribution in glioblastoma and their expression is associated with the mesenchymal state, suggesting that FAP, EphA3 and α‐dystroglycan could be functionally linked." (PMID 33082953, 2020). "Importantly, EPHA3 has been identified as a therapeutic target in glioblastomas using small-molecule inhibitors or targeted antibodies." (PMID 30961526, 2019). "High expression and oncogenic functions of EphA3 have been reported in acute lymphoblastic leukemia (ALL), glioblastoma, gastric cancer, head and neck cancer, and prostate cancer." (PMID 40688499, 2025). "On the contrary, upregulation of EphA3 activates AKT signaling pathway and then facilitates glioblastoma progression." (PMID 36578556, 2022). "Two of the ephrin class RTKs, EPHA3, and EPHB2, also showed overexpression in scattered cases across the glioblastoma subgroups but more prominently in the Multi-RTK and PDGFRA subgroups, respectively." (PMID 34572759, 2021). "To mine the behind mechanism of EphA3-driven melanoma progression, we tested whether EphA3 silence impacts the ERK signaling cascade since anti-EphA3 antibodies could retard glioblastoma progression by modifying ERK1/2 signaling pathway." (PMID 36578556, 2022). "EPHA3 has recently been shown to be highly expressed in glioblastoma, where it remains kinase-dormant due to reduced or absent Ephrin ligand expression, and plays an important role maintaining glioblastoma cells in an undifferentiated state and sustains rapid proliferation." (PMID 28169277, 2017).
glioma (27 papers, 2016 to 2025). A benign or malignant brain and spinal cord tumor that arises from glial cells (astrocytes, oligodendrocytes, ependymal cells). "EPHA3, a membrane-associated receptor, exhibits notable overexpression in the stroma and vasculature of gliomas while maintaining low expression levels in normal tissues." (PMID 39911305, 2025). "EphA3 has been shown to be highly expressed in cells implicated in the initiation of gliomas and is postulated to be playing a role in maintaining these cells in a state of low differentiation, which is important in the pathogenesis of cancer." (PMID 41561543, 2025). "OGM also showed the disruption of the EPHA3 gene, which is implicated in gliomas and overexpressed in 60% of cases, making it a target for glioma therapy." (PMID 39200124, 2024). "EphA3 is a membrane-associated receptor, which is highly expressed in the tumor-initiating cell population in glioma cells, but lowly in normal cells." (PMID 36059989, 2022). "EphA3, a receptor tyrosine kinase, is frequently overexpressed in gliomas, especially in GBM and its mesenchymal subtype." (PMID 41200151, 2025). "Anti-ephrin type-A receptor 3 (EphA3) modified TMZ16e loaded nanoparticles (NPs) were found to improve brain targeting efficiency and anti-glioma activity, as well as reverse TMZ resistance." (PMID 40860814, 2025). "In vivo biodistribution studies in C6 glioma-bearing mice revealed that anti-EPHA3-decorated NPs had robust fluorescence in the tumor tissues." (PMID 39911305, 2025). "Our findings, which show substantial tumor eradication in both pediatric and adult glioma models, validating the potential of EphA3 as a CAR therapeutic target." (PMID 39111833, 2024). "Given the high expression of EphA3 on both glioma tumor cells and the perivasculature surrounding the tumor, we proceeded to create and test a second-generation EphA3-targeted CAR." (PMID 39111833, 2024). "We also validated the cell surface presence of EphA3 using the anti-human EphA3 antibody ifabotuzumab, confirming its expression on various glioma cell lines through flow cytometry." (PMID 39111833, 2024). "Our preclinical data demonstrate that an EphA3-targeted CAR T cell is effective against EphA3-expressing high-grade-gliomas." (PMID 39111833, 2024). "In our study, the utilization of cell surface proteomics to validate EphA3 as a target for glioma treatment has showcased its effectiveness in detecting promising immunotherapy biomarkers and targets directly from fresh primary brain tumors." (PMID 39111833, 2024). "The robust anti-glioma effect displayed by EphA3-CAR T cells, particularly in our in vivo models, aligns with the therapeutic efficacy seen in other studies targeting surface antigens in solid tumors, including lung cancer and melanoma." (PMID 39111833, 2024). "Building on the proven safety profile of EphA3 antibodies in clinical settings, our study provides compelling preclinical evidence supporting the efficacy of EphA3-targeted CAR T cells against high-grade gliomas." (PMID 39111833, 2024). "Further clinical trials, informed by our preclinical data, are essential to determine the real-world applicability and long-term benefits of EphA3-targeted CAR T cell therapies in glioma patients." (PMID 39111833, 2024). "This widespread expression warrants further exploration into EphA3 as a universal therapeutic target beyond high-grade gliomas, potentially benefiting a wider pediatric patient cohort." (PMID 39111833, 2024). "Elevation of either EphA2 or EphA3 maintains glioma cells in a stem-like state by negatively regulating the MAPK/ERK pathway." (PMID 35448036, 2022). "In glioma stem cells, EphA3 is responsible for sustained ERK1/2 activation and promotes its differentiation." (PMID 36578556, 2022). "EPHA3 has abundantly expressed in glioma tumor-initiating cells and plays a crucial role in keeping tumor cells in a less differentiated state, likely altering mitogen-activated protein kinase signaling." (PMID 35264657, 2022).